PTH1R (parathyroid hormone 1 receptor)
Diseases named in the same sentence as PTH1R in open-access papers (continued):
Sharing a sentence is not in itself a finding about the gene and the disease.
diabetes (3 papers, 2013 to 2026). "Targeting PTH1R upregulation and the IL-6 signaling pathway in osteocytes could represent a novel therapeutic approach to mitigating bone complications associated with diabetes." (PMID 41751813, 2026). "Collectively, these results indicate that the renal PTHrP/PTH1R system is upregulated in experimental as well human diabetes, appears to be involved with renal hypertrophy, and adversely affects the outcome of DN." (PMID 23984429, 2013). "Thus, the bone gain induced by activation of the PTH1R with either ligand in diabetes is characterized by increased bone formation in the presence of sustained bone resorption." (PMID 37076478, 2023).
lung carcinoma (3 papers, 2015 to 2023). "In addition to its role in bone, PTH1R has also been shown to mediate cachexia, with adipocyte-specific Pth1r knockout conferring resistance to cachexia driven by kidney failure and lung cancer." (PMID 37046642, 2023). "The finding that PTHrP interferes with lung cancer cell growth by binding to its cell-surface receptor, PTH1R, could have clinical implications." (PMID 26090315, 2015). "It is conceivable that synthetic ligands or small molecule drugs could be designed to activate PTH1R and inhibit lung carcinoma growth." (PMID 26090315, 2015). "Since PTH1R stimulates cAMP as its second messenger in H1944 cells and BEN lung cancer cells, we investigated the direct effects of cell-permeant cAMP compounds on H1944 cell growth." (PMID 26090315, 2015). "The demonstration that PTH1R is necessary for ectopic PTHrP 1–87 to reduce lung cancer cell growth excludes a significant growth inhibitory role for mid-molecule PTHrP domains, i.e. PTHrP 38–87 or PTHrP 67–87." (PMID 26090315, 2015). "We have previously shown that PTH1R activation was coupled to Gs and generation of cAMP in H1944 cells and BEN lung cancer cells, rather than Gq pathways." (PMID 26090315, 2015).
prostate carcinoma (3 papers, 2019 to 2023). A carcinoma that arises from epithelial cells of the prostate gland. "PTH1R, a key regulator in tumor–bone interactions, was upregulated under androgen deprivation in prostate cancer mono-culture and co-cultures." (PMID 31044095, 2019). "Blocking PTH1R rescued TGFBR2 protein levels in osteoblasts and overcame enzalutamide resistance in a coculture system of prostate cancer and osteoblast cells, suggesting PTH1R as a novel target to overcome enzalutamide resistance in prostate cancer bone metastasis." (PMID 37046642, 2023). "Moreover, PTHrP/PTH1R was found to mediate drug resistance in prostate cancer bone metastasis, possibly through facilitating TGFβ type II receptor (TGFBR2) degradation." (PMID 37046642, 2023).
adenoma (2 papers, 2022 to 2025). A neoplasm arising from the epithelium. "The PTH1R mRNA expression level was significantly higher in aldosterone-producing adenomas than in cortisol-producing adenoma but seemed to be similar between ACCs and adenomas." (PMID 35203352, 2022).
Arthritis (2 papers, 2018 to 2023). Inflammation of a joint. "They suggest that autosomal dominant PTH1R mutations that cause PFE may also be linked to arthritis." (PMID 38002872, 2023). "Regarding osteoclast activation, osteoblast receptor PTH1R gene was increased only before arthritis onset in rat AIA (p < 0.01)." (PMID 29472591, 2018).
Blomstrand-type chondrodysplasia (2 papers, 2021 to 2024). "Clinical evaluation of human fetuses affected with embryonic lethal Blomstrand-type chondrodysplasia caused by homozygous loss-of-function mutations in PTH1R exhibit severe alveolar bone distortion." (PMID 39688917, 2024).
breast tumor (2 papers, 2021 to 2023). "Further studies are warranted to explore non-PTH1R mediated actions, which may reveal novel mechanisms by which PTHrP negatively regulates dormancy in bone-disseminated breast tumor cells." (PMID 33828987, 2021). "Lastly, the preclinical data clearly indicate that increased PTHrP expression drives breast tumor cells out of their quiescent state via a mechanism independent of canonical PTH1R activation." (PMID 33828987, 2021).
Cachexia (2 papers, 2023 to 2024). Severe weight loss, wasting of muscle, loss of appetite, and general debility related to a chronic disease. "PTHrP and PTH1R modulation in adipose tissue mediates cachexia (wasting syndrome associated with elevated basal energy expenditure and loss of adipose and muscle tissues) in models of kidney failure." (PMID 38379702, 2024).
chronic kidney disease (2 papers, 2021 to 2023). Impairment of the renal function secondary to chronic kidney damage persisting for three or more months. "In this review, our aim is to show the role of the PTHrP/PTH1R axis in adipose tissue, not only in the adipocyte formation (adipogenesis) but also in its adaptations both to obesity and to diseases that cause the wear and tear of the organism, such as cancer or chronic kidney disease (CKD)." (PMID 34827568, 2021).
gastric cancer (2 papers, 2021 to 2023). A primary or metastatic malignant neoplasm involving the stomach. "Some studies in GC have shown that PTH1R can be expressed in some gastric cancer cell lines, and reduced PTH1R expression can promote gastric hypergastrinemia and gastric neuroendocrine tumors." (PMID 35252217, 2021).
heart failure (2 papers, 2022 to 2025). Inability of the heart to pump blood at an adequate rate to meet tissue metabolic requirements. "In particular, elevated PTH levels have been positively associated with platelet indices in women with symptomatic heart failure, and PTHrP, by interacting with PTH1R on human platelets was shown to potentiate platelet aggregation in response to different stimuli." (PMID 41109132, 2025).
Hypercalciuria (2 papers, 2025). "In mice lacking the parathyroid hormone 1 receptor in the distal tubule, hypercalciuria develops alongside increased Cldn14 expression and this phenotype is rescued upon Cldn14 deletion." (PMID 41325524, 2025).
Hyperglycemia (2 papers, 2021). An increased concentration of glucose in the blood. "Many T2DM patients develop diabetic nephropathy, with renal overexpression of both PTHrP and PTH1R, associated with the development of renal hypertrophy and proteinuria, correlating positively with the level of hyperglycemia." (PMID 34827568, 2021). "In this sense, it has been seen that the expression of PTHrP and PTH1R in the placenta depends on maternal hyperglycemia and obesity and is directly related to adverse pregnancy outcomes." (PMID 34827568, 2021).
hyperphosphatemia (2 papers, 2020 to 2022). Abnormally high level of phosphate in the blood. "A deletion of both PTH1R and Klotho from the kidney proximal tubule (PT-PTH1R/KL−/− mice) led to a severe disturbance of mineral metabolism including hyperphosphatemia at baseline and increased circulating phosphate in response to high phosphate diet." (PMID 32982979, 2020).
hypertrophy (2 papers, 2013 to 2024). Hypertrophy is the increase in the volume of an organ or tissue due to the enlargement of its component cells. "In cardiomyocytes, PTH binds its parathyroid hormone 1 receptor (PTH1R)generating calcium influx within it which stimulates the phospholipase C pathwayinducing myocardial hypertrophy." (PMID 39076335, 2024). "In experimental DN, the overexpression of both PTHrP and the PTH1R contributes to the development of renal hypertrophy as well as proteinuria." (PMID 23984429, 2013).
kidney failure (2 papers, 2022 to 2023). An acute or chronic condition that is characterized by the inability of the kidneys to adequately filter the blood. "According to the literature, two of these differentially expressed genes, namely, paired box 2 (PAX2) [MIM: 167409] and parathyroid hormone 1 receptor (PTH1R) [MIM: 168468], are directly related to kidney failure." (PMID 36371238, 2022).
lung adenocarcinoma (2 papers, 2015 to 2020). A carcinoma that arises from the lung and is characterized by the presence of malignant glandular epithelial cells. "Furthermore, the co-expression of elevated levels of parathyroid hormone-related peptide (PTHrP) and PTH1R significantly correlated with cancer metastasis and mortality in patients with lung adenocarcinoma." (PMID 33316777, 2020). "PTHrP-positive and negative clones of H1944 lung adenocarcinoma cells underwent stable PTH1R knockdown with lentiviral shRNA or transient transfection with ERK1 and ERK2 siRNA." (PMID 26090315, 2015). "In a previous study, we used an expression plasmid to evaluate the proliferative effects of amino PTHrP in H1944 lung adenocarcinoma cells and MV522 lung adenocarcinoma cells, two lines which possess PTH1R but normally do not express PTHrP." (PMID 26090315, 2015).
migraine (2 papers, 2022 to 2025). "Other receptors with possible indirect effects on migraine are parathyroid hormone 1 receptor (PTH1R) and PTH2R, which mediates calcium and phosphate homeostasis, and NPY5R that acts as receptor for neuropeptide Y (NPY), PYY, and PYY, and influences eating." (PMID 35453627, 2022). "In summary, the findings of this study present fresh insights into class B GPCRs like PTH1R and PTH2R, standing out as sturdy and promising targets for innovative therapeutic in conditions such as migraine and various painful disorders." (PMID 40297711, 2025). "Collectively, these findings offer new perspectives on class B GPCRs such as PTH1R and PTH2R, emerging as robust and promising candidates for novel clinical targets in conditions like migraine and other painful disorders." (PMID 40297711, 2025). "Notably, PTH1R and PTH2 were upregulated in female migraine groups, highlighting parathyroid hormone receptors as potential biomarkers for female migraine patients." (PMID 40297711, 2025). "Additionally, PTH1R and PTH2, found in GSEA of the female migraine patients, emerged as significant, interacting with key therapeutic targets in migraine research like CGRP and PACAP." (PMID 40297711, 2025). "PTH1R was upregulated in female migraine without aura versus female controls, while PTH2 was both upregulated between female migraine patients and female controls, as well as between female migraine without aura and controls." (PMID 40297711, 2025).
Osteochondrosis (2 papers, 2018 to 2025). Abnormal growth ossification centers in children. "Polymorphisms in Fas-associated factor 1 (FAF1) gene which enhances apoptosis, and parathyroid hormone type I receptor (PTH1R) gene which regulates cartilage growth and chondrocytic apoptosis, were associated with osteochondrosis lesions in pigs." (PMID 41465565, 2025). "Another study considered this disease as osteochondrosis leading to dysfunctions of bone and joints, caused by polymorphisms in KRT8, FAF, and PTH1R genes in Duroc × Pietrain populations." (PMID 41465565, 2025).
autoimmune disease (1 paper, 2023). A disorder resulting from loss of function or tissue destruction of an organ or multiple organs, arising from humoral or cellular immune responses of the individual to their own tissue constituents. "PTH1R expression was found to be significantly higher in B-lymphocytes in SLE and pSS patients than in healthy controls, suggesting that PTH may activate B cells in patients with autoimmune diseases." (PMID 37841984, 2023).
bladder diseases (1 paper, 2015). "Unfortunately, currently-available PTH1R agonists have systemic side effects that preclude their use for bladder diseases, and bladder-specific derivatives are awaited to allow the clinical translation of the PTHrP-PTH1R axis for treating bladder diseases." (PMID 25604159, 2015).
bone-tumor (1 paper, 2018). "Both PTH1R and CaSR participate in the bone-tumor vicious cycle and influence the skeletal metastatic niche." (PMID 30151009, 2018).
brain inflammation (1 paper, 2023). "At cellular level, PTH1-34 binds to PTH1R not only in osteoblasts but also in astrocytes, suppressing cellular senescence, systemic inflammation, and brain inflammation." (PMID 36918976, 2023).
cardiomyopathies (1 paper, 2020). "Some of these genes, including PTH1R, S100A4 and ADAM15, have been reported to be differentially expressed in DCM or other types of cardiomyopathies." (PMID 31948008, 2020).
Cognitive impairment (1 paper, 2016). Abnormal cognition is characterized by deficits in thinking, reasoning, or remembering. "This case represents the extreme end of the spectrum of cognitive impairment in PTH dysfunction and defines a possible novel form of PHP1b resulting from the impaired interaction between PTH and PTH1R." (PMID 27415614, 2016).
glomerular diseases (1 paper, 2025). "The interaction between PTHLH and PTH1R has been implicated in renal tubulointerstitial damage and glomerular diseases, including DKD." (PMID 40690456, 2025).
Hypertension (1 paper, 2018). The presence of chronic increased pressure in the systemic arterial system. "Therefore, the regulation of PTH1R shown in this study seems to be associated with hypertension." (PMID 30198211, 2018).
hypothyroidism (1 paper, 2023). Abnormally low levels of thyroid hormone. "The PTH1R gene has been shown to be expressed in the thyroid gland and in one study human carriers of a mutation in this gene exhibited hypothyroidism." (PMID 36845393, 2023).
invasive breast carcinoma (1 paper, 2023). A carcinoma that infiltrates the breast parenchyma. "Studies have shown that PTHrP and PTH1R are co-expressed in many invasive breast carcinomas." (PMID 36692956, 2023).
Kidney Cyst (1 paper, 2021). Abnormal fluid filled sac within the kidney, either acquired or congenital. "One possible mechanism by which cinacalcet suppressed kidney enlargement in the present cohort is by lowering the level of PTH in serum, which leads to reduced tubular activation of PTH1R and cAMP production in kidney cyst cells." (PMID 33976330, 2021).
laryngeal carcinoma (1 paper, 2022). Carcinoma that arises from the laryngeal epithelium. "PTHrP and PTH1R were expressed at cytoplasmic level in normal larynx epithelium and more differentiated laryngeal cancer cells, suggesting an autocrine/paracrine role of PTHrP in squamous cell differentiation of well differentiated tumors with good prognosis." (PMID 35761298, 2022). "In fact, as revealed by the survival analyses, the expected survival probability of patients with laryngeal cancer expressing PTHrP seems correlated with co-expression of PTH1R." (PMID 35761298, 2022).
laryngeal squamous cell carcinoma (1 paper, 2022). A squamous cell carcinoma that arises from the larynx. "Therefore, we studied the expression of PTHrP and its receptor, parathyroid hormone-related peptide receptor type 1 (PTH1R), in primary locally advanced laryngeal squamous cell carcinomas (LALSCC) also in relation to the clinical outcome of patients." (PMID 35761298, 2022).
metastatic tumors (1 paper, 2023). "When metastatic tumors were compared with primary tumors, 1 study showed significant reduction in Pth1r levels, and there was no change in a second study." (PMID 36692956, 2023).
myeloma (1 paper, 2010). "In two myeloma cells lines (CAG and ARP1) and primary myeloma plasma cells from seven patients, qRT-PCR was used to confirm that type-1 PTH receptor (PTH1R) was not expressed by myeloma cells." (PMID 21188144, 2010).
neuroblastic tumor (1 paper, 2019). A group of nervous system tumors which display neuronal differentiation. "On the other hand, PTHLH is highly expressed in well‐differentiated, Schwannian stroma‐rich neuroblastic tumors and high levels of PTH1R expression are associated with MYCN nonamplified, benign neuroblastomas." (PMID 31293052, 2019).
overactive bladder (1 paper, 2015). Symptom of overactive detrusor muscle of the urinary bladder that contracts with abnormally high frequency and urgency. "In addition, the PTHrP-PTH1R axis could be a target for treating milder damage in bladders retaining PTH1R expression, including overactive bladder, which affects a far larger percentage of the population than severely diseased bladder." (PMID 25604159, 2015).
paraganglioma (1 paper, 2022). A benign or malignant neoplasm arising from paraganglia located along the sympathetic or parasympathetic nerves. "Among the seven down-regulated GPCRs in paraganglioma, Arginine Vasopressin Receptor 1A (AVPR1A), ACTH receptor, MC2R, and PTH1R were the target of 2 to 4 drugs each." (PMID 35203352, 2022).
parathyroid adenomas (1 paper, 2025). "PTH1R showed weak but consistent stromal expression in the thymus, while in parathyroid adenomas it was strong and apically accentuated, outlining clusters of active chief cells." (PMID 41373711, 2025). "In contrast, parathyroid adenomas exhibited strong, polarized staining, with an apical distribution in clusters of chief cells, indicating an active involvement of PTH1R in pathological glandular proliferation and secretory modulation." (PMID 41373711, 2025).
pulmonary fibrosis (1 paper, 2026). Chronic progressive interstitial lung disorder characterized by the replacement of the lung tissue by connective tissue, leading to progressive dyspnea, respiratory failure, or right heart failure. "In a preclinical evaluation using a bleomycin-induced pulmonary fibrosis mouse model, attenuating effects against pulmonary fibrosis were observed using neutralizing antibodies, peptides, and gene silencing strategies targeting the PTHrP1-34/parathyroid hormone 1 receptor axis." (PMID 41724741, 2026).
sarcoma (1 paper, 2024). A usually aggressive malignant neoplasm of the soft tissue or bone. "PTH1R encodes the parathyroid 1 receptor and, like IGFBP5, was also among the DEG upregulated in FUS/EWSR1-TFCP2 sarcoma compared with other RMS types." (PMID 38168093, 2024). "Furthermore, PTH1R, encoding the parathyroid 1 receptor, was also highly expressed in FUS/EWSR1-TFCP2 sarcomas and strongly induced by TFCP2 fusions in immortalized cells." (PMID 38168093, 2024).
selenium deficiency (1 paper, 2024). A nutritional deficiency disease resulting from inadequate selenium levels in the body, which can lead to impaired function of selenoproteins essential for antioxidant defense and thyroid hormone metabolism. "Our analysis identified multiple DEGs that may be associated with cartilage development and selenium deficiency, such as PTH1R and SAA1." (PMID 38673933, 2024).